ATOH1 (atonal bHLH transcription factor 1)
Diseases named in the same sentence as ATOH1 in open-access papers (continued):
Sharing a sentence is not in itself a finding about the gene and the disease.
tumor (continued). "Furthermore, ATOH1‐overexpressing NCI‐N87 cells showed lower tumorigenicity and slower tumor growth than control cells." (PMID 37824217, 2023). "According to these results, the expression levels of NR3C2, KLF4, CASZ1, FOXD2, ATOH1, and RORC reduce in CRC and may function as tumor suppressors." (PMID 36344988, 2022). "We speculate that ATOH1 may influence the efficacy of ICIs therapy in patients with COAD by affecting the immune microenvironment and immunogenicity of the tumor." (PMID 35836254, 2022). "Given its role in cellular proliferation and CRC tumorigenesis and progression, the present study investigated whether tumor expression of Notch target genes, HES1 and ATOH1, may be used as predictors of response to CRT in RC patients." (PMID 34582650, 2021). "They identified both ATOH1 and LGR5 double positive tumor cells as well as LGR5 single positive tumor cells, suggesting that colitic tumors are mosaic and consisted of a heterogenous population of tumor stem cell." (PMID 33541282, 2021). "This phenotype was completely abrogated in the absence of Atoh1, a molecule that is also considered to act as a tumor suppressor in CRC." (PMID 28086833, 2017). "To assess whether the inhibition of tumor growth involved changes in the levels of proteins important for GCP development, we assayed expression of ATOH1." (PMID 24303070, 2013). "The second exception was the significantly lower ATOH1 mRNA levels (p = 4.38 × 10−7) in all VP-MCC-like tumors than VP-MCC cell lines, which might be due to the incipient tumor status of VP-MCC-like tumors versus the advanced cancer stage of these VP-MCC cell lines." (PMID 40940897, 2025). "Importantly, neither Krt5-driven expression of MCPyV LT nor co-expression of MCPyV-LT with Atoh1 or with sT and Atoh1 did alter the phenotype of the mice—in particular tumor growth in the Atoh1/sT setting—questioning the significance of LT with respect to tumor formation." (PMID 36672392, 2023). "That the ATOH1 subtype of SCLC CDX shares features with NE SCLC and with MCC, another NE cancer, is perhaps not surprising and might indicate convergent tumor evolution." (PMID 40305287, 2025). "While ATOH1 CDXs expressed neither ASCL1 nor POU2F3, ATOH1 was expressed alone (CDX17P) or in combination with NEUROD1 at the transcript and protein levels (CDX25, 78% positive tumor cells; CDX30P, 78% positive tumor cells; CDX17, moderate NEUROD1 expression, 30% positive tumor cells)." (PMID 40305287, 2025).
cancer (23 papers, 2006 to 2025). A tumor composed of atypical neoplastic, often pleomorphic cells that invade other tissues. "We further elucidated the molecular mechanisms by which ATOH1 deficiency induces CSC‐like properties that drive cancer progression in vitro and in vivo." (PMID 37824217, 2023). "Taken together, the results demonstrate that ATOH1 loss promotes cancer stemness through the ATOH1/GAS1/RET/AKT/mTOR signaling pathway in GAC, thus providing a potential therapeutic strategy for AKT/mTOR inhibitors in GAC patients with ATOH1 deficiency." (PMID 37824217, 2023). "In summary, deletions and epigenetic silencing via methylation combine to cause loss-of-function mutations of the human ATOH1 locus in primary human cancers." (PMID 19243219, 2009). "As expected, most genes in this cluster also have high values for semantic features associated with cluster A (cancer), since all the genes except ATOH1 were also annotated with the 'Cancer' category by the original authors." (PMID 16438716, 2006). "In addition, the ATOH1 should be subject to loss-of-function mutations in a significant number of human cancer patients." (PMID 19243219, 2009). "Interestingly, ATOH1 has been associated with various kinds of cancers including colon cancer." (PMID 25950549, 2015). "Given the remarkable evolutionary conservation of ato/Atoh1 function in cancer development, we decided to analyze whether loss of the human ortholog, ATOH1, might be selected for during malignant transformation in human cancer." (PMID 19243219, 2009). "Total of 17 cells in cluster 6 were further defined as cancer cells with Paneth cell properties (Paneth+) or goblet cell properties (Goblet+) using the relevant marker genes expression, Lyz1, Muc2and Atoh1." (PMID 38659853, 2024). "ATOH1 is a cancer suppressor gene silenced in most kinds of tumors except gastrointestinal tumors, where it shows high expression." (PMID 35836254, 2022). "In mouse and human cancer cell lines, the mammalian Ato ortholog ATOH1 appears to act by a similar mechanism." (PMID 25344916, 2014). "Normal lifespan and fecundity of Atoh1trhlmice provide a complementary model to facilitate elucidation of ATOH1 function in hearing,central nervous system and cancer biology." (PMID 24265785, 2013). "All of these genes are present in the Census database of cancer genes except for the recently discovered cancer genes ATOH1 and PHF6." (PMID 22675565, 2012). "To better understand the role that ATOH1 plays in cancer, we sought to determine the molecular mechanism by which it acts to suppress the formation and progression of tumors." (PMID 19243219, 2009). "Similarly, SOX2 aids chromatin remodelling, regulating cancer progression genes and preserving cancer stem cell characteristics, further solidifying the combined role of ATOH1 and SOX2 in MCC oncogenesis." (PMID 40589575, 2025). "Second, ATOH1 is relatively high only in gastrointestinal tumors and is rarely expressed in other types of tumors, so it was difficult for us to validate our findings using datasets treated with ICIs from other cancer types." (PMID 35836254, 2022). "To address a putative epigenetic transcriptional silencing mechanism, we began by asking whether transcription could, in principle, be initiated from the ATOH1 locus in cancer cells." (PMID 19243219, 2009). "Thus, the ATOH1 locus is methylated in cancer patients and derived cell lines, and this methylation can be reversed, resulting in the transcriptional reactivation of the locus." (PMID 19243219, 2009). "This provides the opportunity to test whether transcription could be activated from the ATOH1 locus by ATOH1 itself in normal versus cancer cells." (PMID 19243219, 2009). "How does ATOH1 expression lead to JNK activation in cancer cells?" (PMID 19243219, 2009).
cancer (continued). "In contrast to the cancer cell lines, endogenous ATOH1 is up-regulated 38-fold by Atoh1." (PMID 19243219, 2009). "Next we asked whether the molecular mechanism of ATOH1 function in human cancer is similar to the mouse." (PMID 19243219, 2009). "Furthermore, such treatment in combination with Notch inhibitors may enhance re-expression of the ATOH1-driven differentiation program and synergistically inhibit cancer growth." (PMID 19243219, 2009). "Our data obtained from Atoh1-CreER; Kif20afl/fl single and Atoh1-CreER; Ptcfl/fl; Kif20afl/fl double-knockout mice together showed that KIF20A functions similarly in normal and cancer-initiating GNPs to maintain their proliferative potential." (PMID 33976373, 2021). "Similarly, treatment of CRC and MCC patients whose tumors show epigenetic silencing of ATOH1 with DNA methyltransferase inhibitors might prove a powerful avenue for therapy, because it appears to be sufficient to restore ATOH1 expression and induce cancer cell death." (PMID 19243219, 2009). "Cluster B (development) contains all the development and cancer genes with the exception of TGFB1 (which is in cluster A), together with ATOH1 (annotated as 'development')." (PMID 16438716, 2006). "In cancers, Atoh1 was frequently hyper-expressed in mucinous cancers, but rarely in non-mucinous cancers, indicating a possible involvement of Atoh1 in MCA tumorigenesis." (PMID 29786668, 2018). "For several TFs and for each of the three patients, inactivation events were seen across most, if not all, cancer cells: for instance, this was the case for ATOH1, or the autophagy inducer TRIM3162, thus implicating disruption of this novel and specific autophagy pathway in colon cancer." (PMID 33083012, 2020). "Using the 5 patients with both normal and cancer cells profiled, we estimated the frequency of inactivation of all 56 colon-specific TFs across the 5 patients, which revealed that CDX2 and TRIM31 were inactivated in 80% of the patients, whereas ATOH1, HNF4A, CDX1, and TBX10 were inactivated in 60%." (PMID 33083012, 2020). "Since the trhl mutant mice have a normal life span, unlike previous Atoh1-nullmutations, which are perinatally lethal, we can take advantage of this newmodel to investigate many aspects of downstream hearing and balance pathophysiology, molecular biology, proteomics and cancer biology." (PMID 24265785, 2013).
infection (18 papers, 2012 to 2024). The state of being infected such as from the introduction of a foreign agent such as serum, vaccine, antigenic substance or organism. "The HF diet also exacerbated small intestinal goblet cell hyperplasia in association with elevated expression of the Atoh1 gene, which regulates intestinal secretory cell proliferation, while in the colon it worsened the mucus granule depletion induced by the infection." (PMID 34552170, 2021). "After Ad-Atoh1 infection, the number of PVALB+ cells was significantly increased in both the sensory epithelium (13.02 ± 1.076 cells/100 μm sensory epithelium, n = 9) and the limbus region (2.76 ± 0.63 cells/2, 500 μm2 limbus region, n = 6)." (PMID 35082601, 2021). "We noticed that only a small portion of GFP+ cells turned out to be MYO7A+ HCLCs in both the sensory epithelial region and the limbus region after the infection of Ad-Atoh1 (16.00 ± 2.18% for the sensory epithelium, 12.57 ± 3.29% for the spiral limbus region)." (PMID 35082601, 2021). "In contrast, PVALB+ HCLCs were detected in the OHC region after Ad-Atoh1 infection and all of them were Tm-red+." (PMID 35082601, 2021). "The rate of Brn3c/Atoh1 double-positive cells from the J1-6d infection scheme was significantly lower than that of the cells infected with NC-shRNA." (PMID 34940631, 2021). "In contrast, overexpression of all 16 TFs led to Atoh1-nGFP activation in 1.7% (± 0.3) of MEFs at 14 days post infection." (PMID 32602462, 2020). "We also observed that infection of supporting cells with Ad-tdTomato-Atoh1 virus up-regulated a significant number of genes (440 genes) that were neither present in mature hair cells, nor up-regulated by hair cell damage and culture alone." (PMID 31033441, 2019). "To determine if Atoh1 promotes dividing adult SCs to transdifferentiate to HCs, we performed a triple infection with mixed ad-Myc/ad-Cre/ad-Atoh1 in the cultured adult Rosa-NICD cochlea and analyzed HC regeneration." (PMID 31797926, 2019). "In Dox-treated rtTA/tet-Myc/tet-NICD cochlea followed by ad-Atoh1 infection, we found ectopic HC-like cells (eHCs, defined as regenerated HC-like cells), labeled with HC markers ESPN and PVALB, regenerated in different cochlear areas including the IHC region." (PMID 31797926, 2019). "(E) Infection of supporting cells with Ad-Atoh1 virus induces expression of the hair cell marker Myosin7a." (PMID 31033441, 2019). "We generated heat maps to observe the behavior of 2619 supporting cell-enriched genes in utricle supporting cells following hair cell killing and culture after infection with either Ad-tdTomato or Ad-tdTomato-Atoh1 virus." (PMID 31033441, 2019). "We found that induction of HES1 and OLFM4 and the down-regulation of ATOH1 transcript levels was consistent with the increased Notch-1 signalling in crypts at the peak of infection." (PMID 28323899, 2017). "Additionally, infection with C. parvum resulted in downregulation of a number of genes, including some involved in intestinal differentiation pathways, such as ATOH1 or BMP3." (PMID 38189373, 2024). "Moreover, the fluorescence intensities of Brn3c and Atoh1 in the Brn3c/Atoh1 double-positive cells from the J2+D1-5d infection scheme were much higher than the other four infection schemes." (PMID 34940631, 2021). "These GFP+ cells were the cells with Atoh1 transcriptional activity due to Ad-Atoh1 infection." (PMID 35082601, 2021). "We used adenovirus carrying CMV promoter-driven human ATOH1 (Ad-Atoh1) to infect cultured adult Atoh1-GFP transgenic mouse cochleae, whereas adenovirus carrying a V5 tag (Ad-V5) was used as the control for infection." (PMID 35082601, 2021). "To assess the morphological properties of iHCs we performed immunostaining at 14 days post-infection following SAPG reprogramming, which is approximately 10 days after initial Atoh1-nGFP detection." (PMID 32602462, 2020). "(C) Images of MEFs reprogrammed with Six1, Atoh1, Pou4f3, and Gfi1 (SAPG) fixed at 14 days post infection (dpi)." (PMID 32602462, 2020).
infection (continued). "Adding Dox to cultured adult rtTA/tet-Myc/tet-NICD cochleae for three days and following with ad-Atoh1 infection lasting for 14 days, we detected no new HCs in the Dox-only-treated control cochlea." (PMID 31797926, 2019). "It was identified that the formation of EHCLCs was Atoh1 dependent, as no EHCLCs formed upon infection by GFP alone." (PMID 24788407, 2014). "Ten days after transduction with Ad-Atoh1-tdTomato virus, more than 80% of the infected cells expressed Myo7a, while cells infected with Ad-tdTomato virus remained Myo7a negative ten days after infection." (PMID 31033441, 2019).
ATOH1 also shares sentences with these, for which no sentence is quoted: viral infection (3 papers); aortic atherosclerosis (2); atherosclerosis (2); cerebellar tumor (2); colon adenocarcinoma (2); gastrointestinal tumors (2); small cell lung carcinoma (2); adenocarcinoma (1); age-related hearing loss (1); alexithymia (1); amebiasis (1); astrocytoma (1); autoimmune uveitis (1); Autoimmunity (1); bacterial infection (1); brain cancer (1); campomelic dysplasia (1); cardiac hypertrophy (1); cardiovascular disease (1); cerebellar ataxia (1); childhood tumor (1); Colonic Carcinomas (1); epilepsies (1); eye tumors (1); Familial adenomatous polyposis (1); gastric adenocarcinoma (1); hematological disease (1); inner ear disorder (1); intestinal diseases (1); iron deficiency (1).
A further 11 diseases each share a sentence with ATOH1 in 1 paper.